SDC1 (syndecan 1)
Diseases named in the same sentence as SDC1 in open-access papers (continued):
Sharing a sentence is not in itself a finding about the gene and the disease.
preeclampsia (11 papers, 2015 to 2022). Preeclampsia is a hypertensive disorder of pregnancy that is characterized by new-onset hypertension with proteinuria presenting after 20 weeks of gestation, and depending on mild or severe forms may initially present with severe headache, visual disturbances, and hyperreflexia. "This implies that SDC-1 levels are intricately linked to the placental pathology, which makes preeclampsia distinct from gestational hypertension." (PMID 35836437, 2022). "Clinical studies correlated an altered Sdc-1 expression with the risk of pregnancy diseases like preeclampsia, fetal growth restriction and preterm delivery, pregnancy complications which in turn are allocated most likely due to insufficient invasion." (PMID 25830352, 2015). "We hypothesize that the interaction between soluble syndecan-1 and its associated GAGs synergistically contributes to sFLT1-induced BP elevation characteristic of preeclampsia." (PMID 33623064, 2021). "In conclusion, dermatan sulphate is significantly elevated in preeclampsia and inversely correlated with soluble syndecan-1 and BP, suggesting that the association of soluble syndecan-1 with BP in preeclampsia might be mediated by dermatan sulphate." (PMID 33623064, 2021). "In the present study, we assess whether circulating amounts of soluble syndecan-1 and associated GAGs are altered in preeclampsia compared to normotensive pregnancies and whether Sdc1 deficient mice have a differential BP response to sFlt1 compared to wild type controls." (PMID 33623064, 2021). "Our initial hypothesis was that plasma soluble Sdc1 levels would increase with advancing normal pregnancy, and increase significantly more so before and after the onset of preeclampsia in association with reduction of Sdc1 immunoreactivity on STB of villous placenta." (PMID 27299886, 2016). "The rationale was based on the concept that the increased systemic inflammation thought to underlie the pathogenesis of preeclampsia, representing an accentuation of the normal inflammatory response to pregnancy, might be a stimulus for increased Sdc1 shedding." (PMID 27299886, 2016). "Syndecan-1 expression in the kidney of rats was further measured, the results of which were consistent with serum Syndecan-1 level that preeclampsia rats have much higher Syndecan-1 than control animals." (PMID 35635041, 2022). "The results showed that the levels of both Syndecan-1 and HS were remarkably rose in serum of preeclampsia rats compared with normal animals." (PMID 35635041, 2022). "The serum concentration of syndecan-1 was found to correlate positively with the gestational age in all pregnancies and negatively with the systolic blood pressure in patients with preeclampsia." (PMID 35836437, 2022). "In women with preeclampsia circulating concentrations of syndecan-1 have been shown to be similar, decreased or increased compared with normotensive controls." (PMID 36311221, 2022). "This article pioneers in systematically reviewing the relationship of antepartum levels of the soluble ectodomain portion of SDC-1 in the serum of pregnant women with preeclampsia." (PMID 35836437, 2022). "Results of Syndecan-1 assay were similar to HS that preeclampsia rats have higher level of Syndecan-1 in serum 1, 3, and 5 days after model made which was decreased by Ropivacaine significantly after 3 and 5 days of treatment (P < 0.05)." (PMID 35635041, 2022). "Preeclampsia rats treated with intraspinal injected ropivacaine attenuated preeclampsia-induced kidney injury as Syndecan-1 and HS were decreased in serum, Syndecan-1 expression was suppressed as well as α7nAChR was activated in the kidney." (PMID 35635041, 2022). "Our results further verified that GCX indicated by Syndecan-1 and HS was significantly increased accompanied with kidney injury induced by preeclampsia." (PMID 35635041, 2022).
preeclampsia (continued). "Plasma samples taken at inclusion after diagnosis (preeclampsia cases) or at admission for delivery (normotensive controls) were analyzed with ELISA for syndecan-1, hyaluronic acid and thrombomodulin and compared between groups." (PMID 36311221, 2022). "The aim of this study was to investigate plasma concentrations of syndecan-1, hyaluronic acid and thrombomodulin in preeclampsia of different severity." (PMID 36311221, 2022). "The expression of Syndecan-1 in the kidney of preeclampsia rats treated with Ropivacaine was downregulated dramatically." (PMID 35635041, 2022). "The expression of Syndecan-1 in kidney of preeclampsia rats was found upregulated significantly in the present study." (PMID 35635041, 2022). "The alteration in the cell surface expression with preeclampsia manifests as a decrease in soluble SDC-1 levels, measured as the serum SDC-1." (PMID 35836437, 2022). "Since soluble SDC-1 retains its property to bind cytokines, decreased shedding can promote or exaggerate maternal systemic inflammation related to preeclampsia." (PMID 35836437, 2022). "The results of HS and Syndecan-1 detection suggested that glycocalyx mediated vascular endothelial cell injury occurred in preeclampsia model rats which were attenuated by Ropivacaine." (PMID 35635041, 2022). "SDC-1 likely plays a crucial role in the pathogenesis of preeclampsia and increases significantly throughout gestation." (PMID 35836437, 2022). "This article is the first systematic literature review that evaluates the relationship between the antepartum serum levels of the syndecan-1 and preeclampsia." (PMID 35836437, 2022). "In preeclampsia, both soluble syndecan-1 and dermatan sulphate are inversely correlated with blood pressure (BP)." (PMID 33623064, 2021). "Plasma heparan sulphate and dermatan sulphate were strongly correlated with soluble syndecan-1 in women with preeclampsia." (PMID 33623064, 2021). "Additionally, MMP-7 can act as a sheddase for syndecan-1, a major transmembrane heparan sulfate proteoglycan expressed on the surface (glycocalyx) of epithelial, endothelial, and syncytiotrophoblast cells, which are implicated in the pathophysiology of preeclampsia." (PMID 31163045, 2019). "Gestational age at delivery correlated significantly with circulating soluble Sdc1 (preeclampsia r = 0.49, P<0.05; control: r = 0.64, P<0.01), and with villous mRNA in controls (r = 0.51, P<0.03)." (PMID 27299886, 2016). "Expression of Sdc1 on the STB microvillous membrane is reportedly reduced in preeclampsia and iatrogenic IUGR with fetal compromise, compared to uncomplicated pregnancy." (PMID 27299886, 2016). "In a different set of preeclampsia cases and controls we compared villous placental Sdc1 expression profile, and looked for correlations with clinical variables and plasma Sdc1." (PMID 27299886, 2016). "Mirroring the differences in maternal circulation, preeclampsia is characterized by reduced expression Sdc1 on the syncytiotrophoblast of placental villi." (PMID 27299886, 2016). "Using an antibody (MI15) recognizing an extracellular epitope of the core protein, the authors reported focally reduced or absent Sdc1 immunoreactivity on the apical microvillous surface despite an overall increase in cytoplasmic Sdc1 in preeclampsia." (PMID 27299886, 2016). "Clinical characteristics of uncomplicated pregnancy control (n = 19), gestational hypertensive (n = 9), and preeclampsia (n = 9) groups; for comparison of soluble Sdc1 in gestational age-matched, 2nd trimester maternal plasma." (PMID 27299886, 2016). "We compared Sdc1 protein expression in villous tissue homogenates by Western blot, using all available samples from the same patients (n = 16 preeclampsia, 16 controls)." (PMID 27299886, 2016). "Circulating soluble Sdc1 was ~2.5-fold lower in women with preeclampsia [median ng/mL (range): preeclampsia 281(101–2237) compared to controls 705 (243–2861); P<0.01]." (PMID 27299886, 2016).
preeclampsia (continued). "Soluble Sdc1 is significantly lower before the clinical onset of preeclampsia, with reduced expression of Sdc1 in the delivered placenta, suggesting a role for glycocalyx disturbance in preeclampsia pathophysiology." (PMID 27299886, 2016). "Although we cannot rule out the presence of subclinical disease at the time of blood sampling, these data suggest that Sdc1 dysregulation is an early event in preeclampsia pathogenesis." (PMID 27299886, 2016). "In contrast, median soluble Sdc1 values in the preeclampsia sub-group with AGA infants [584 (159–1529)] only trended lower than controls (P = 0.18)." (PMID 27299886, 2016). "Soluble Sdc1 was measured in pre-delivery maternal plasma, available from most of these patients (n = 17 preeclampsia, n = 19 controls)." (PMID 27299886, 2016). "On average, women who later develop preeclampsia have lower levels of soluble Sdc1 in maternal plasma at 20 weeks’ gestation (before clinical disease onset) compared to women with uncomplicated pregnancy or gestational hypertension." (PMID 27299886, 2016). "Syncytiotrophoblast Sdc1 immunostaining intensities, and mRNA content in villous homogenates, were lower in preeclampsia vs. controls (P<0.05)." (PMID 27299886, 2016). "Our immunohistochemical, Western blot and mRNA data collectively indicate a decrease in placental Sdc1 expression with preeclampsia." (PMID 27299886, 2016). "The two preeclampsia patients who later delivered SGA infants had mid-gestation soluble Sdc1 values (161 and 217 ng/mL), straddling the overall preeclampsia group median (174 ng/mL)." (PMID 27299886, 2016). "By densitometry, median Sdc1 band intensities were lower in the preeclampsia group (P< 0.05), consistent with the immunohistochemistry scores." (PMID 27299886, 2016). "Our mid-pregnancy data are consistent with a possible contribution of soluble Sdc1 to the pathogenesis of preeclampsia." (PMID 27299886, 2016). "The Sdc1 intensity score for Sdc1 on syncytiotrophoblast was significantly lower in preeclampsia (n = 19) [2.0 (1.0–3.5)] vs. controls (n = 25) [(3.0 (1.0–4.0)] (P<0.001, Unadjusted Rank ANCOVA)." (PMID 27299886, 2016). "The data on circulating concentrations of syndecan-1 in preeclampsia are conflicting." (PMID 36311221, 2022). "SDC-1 transport to the cell surface is dependent on intact cytoskeletal proteins like actin, which may be disrupted in preeclampsia and results in increased retention within the cells." (PMID 35836437, 2022). "Extra-endothelial origin such as the placenta may be overshadowing the contribution of syndecan-1 concentrations in plasma from an injured endothelium in preeclampsia." (PMID 36311221, 2022). "Extremely low levels of soluble syndecan-1 may be helpful as a predictor for the development of preeclampsia during gestation." (PMID 35836437, 2022). "Our results showed that kidney injury was obviously in preeclampsia rats with proteinuria, endothelial damage, higher apoptosis rate, increasing levels of Syndecan-1 and HS in serum, upregulated Syndecan-1 expression but downregulated α7nAChR expression in kidney." (PMID 35635041, 2022). "Consequently, the placental expression of SDC-1 changes, which precedes the development of clinical features in preeclampsia." (PMID 35836437, 2022). "We then measured the level of Syndecan-1 and HS in the serum of preeclampsia rats." (PMID 35635041, 2022). "The classical sFlt1 induced rise in blood pressure was absent in syndecan-1 deficient mice indicating that syndecan-1 is a prerequisite for sFlt1 induced increase in blood pressure central to preeclampsia." (PMID 33623064, 2021). "Higher protein expression of other SDCs (notably SDC1) in placental tissue, and lower levels in maternal plasma, have been associated with pregnancies that subsequently develop preeclampsia with or without HELLP51." (PMID 31308409, 2019).
preeclampsia (continued). "The authors suggested that abnormal cytoplasmic accumulation/retention of Sdc1 below the apical membrane occurs with preeclampsia, and that this might contribute to the observed reduction of soluble Sdc1 in maternal plasma." (PMID 27299886, 2016). "Given evidence for a role of inflammation in the pathogenesis of preeclampsia we originally hypothesized that soluble Sdc1 would be elevated in women with the syndrome." (PMID 27299886, 2016). "Comparing the preeclampsia and uncomplicated pregnancy placentas exposed to labor, the intensity score for Sdc1 on syncytiotrophoblast was significantly lower in preeclampsia with labor (n = 16) [2.25 (2.0–3.0)] vs. controls with labor (n = 13) [(3.0 (2.5–4.0)] (P<0.03)." (PMID 27299886, 2016). "Further studies are needed to determine the effects of altered Sdc1 kinetics on pregnancy physiology and its significance for placental and vascular glycocalyx integrity and function in normal pregnancies and those complicated by preeclampsia." (PMID 27299886, 2016). "Although speculative at this point, the lower soluble Sdc1 in women destined to develop preeclampsia, and evidence of downregulation of syncytiotrophoblast Sdc1 in women with the syndrome, may be another expression of this stress response." (PMID 27299886, 2016). "Soluble Sdc1 correlated with infant birth weight percentile in women with gestational hypertension (r = 0.69, P<0.05) and their controls (r = 0.79, p<0.03), but the correlation was marginal in preeclamptic women (r = 0.45, P = 0.07) and not significant in their controls (r = 0.05, P = 0.84)." (PMID 27299886, 2016). "Because of the observational nature of our study we cannot establish a causal relationship between maternal plasma Sdc1 levels and the subsequent development of preeclampsia." (PMID 27299886, 2016). "The reduced placental expression of SDC1 could be correlated with intrauterine growth restriction, preeclampsia, and hemolysis, elevated liver enzymes and low platelet count (HELLP) syndrome, whereas elevated placental SDC1 expression reduced the risk for preterm birth." (PMID 30825879, 2019). "Contrary to hypothesis, we found that soluble Sdc1 concentrations are significantly lower during the second trimester, ~16 weeks before clinically apparent preeclampsia, and in the 3rd trimester after disease onset but before any labor, compared to controls with uncomplicated pregnancy." (PMID 27299886, 2016). "Additionally, because of its ability to bind various growth factors like fibroblast growth factor 2, hepatocyte growth factor, VEGF, and transforming growth factor-beta, decreased levels of SDC-1 may also play a central role in the antiangiogenic state of preeclampsia." (PMID 35836437, 2022). "In addition, sFlt1 induces BP elevation in wild type mice, but not in syndecan-1 deficient mice, indicating that syndecan-1 may be an important mediator in sFLT1 induced blood pressure elevation in preeclampsia and anti-angiogenic hypertension." (PMID 33623064, 2021). "Before the onset of preeclampsia, some studies have shown decreased plasma concentrations of syndecan-1 compared to normotensive pregnancies, while others have not." (PMID 36311221, 2022). "In contrast, the women who developed SGA without preeclampsia, (n = 57) or indeed women who developed preeclampsia without SGA (n = 32) displayed no significant changes in circulating syndecan-1 relative to controls." (PMID 34400721, 2021). "There is one contrasting report of an overall increase in expression of Sdc1 on STB, accompanied by significantly lower soluble Sdc1 concentrations in maternal serum, in preeclampsia (with or without HELLP syndrome) compared to normal controls." (PMID 27299886, 2016). "We compared soluble Sdc1 in gestational age-matched, mid-pregnancy (range 18–24 weeks) samples from 9 women who later developed preeclampsia, 9 who developed gestational hypertension (without proteinuria), and 19 with uncomplicated pregnancy." (PMID 27299886, 2016).
preeclampsia (continued). "Soluble Sdc1 was lower at mid-pregnancy in women who later developed preeclampsia (P<0.05), but not gestational hypertension, compared to controls, and remained lower at late pregnancy in preeclampsia (P<0.01) compared to controls." (PMID 27299886, 2016). "We measured plasma soluble Sdc1 one year after completed pregnancy, comparing 17 non-pregnant women with a history of preeclampsia compared to 19 women with a history of uncomplicated pregnancy." (PMID 27299886, 2016). "Soluble Sdc1 was lower in preeclampsia (P<0.02, Rank ANCOVA), but not after adjustment for gestational age (P = 0.20)." (PMID 27299886, 2016). "Only two preeclampsia patients in our entire study manifested elevated liver enzymes and thrombocytopenia (hemolysis data not available); soluble Sdc1 values in these patients were below the preeclampsia median." (PMID 27299886, 2016). "Soluble Sdc1 did not significantly differ post-pregnancy between women with a history of preterm vs. term preeclampsia, or between women with a history of preeclampsia with SGA vs. AGA infants (data not shown)." (PMID 27299886, 2016). "Soluble Sdc1 concentrations were significantly lower, weeks before clinical development of preeclampsia [median ng/mL 174 (range 48–353)], but not gestational hypertension [242 (111–1187)], compared to controls [272 (78–1463)] (P<0.05, Kruskal-Wallis, post hoc Dunn’s)." (PMID 27299886, 2016). "Finally, to test for lasting constitutional differences, we measured plasma soluble Sdc1 one year after delivery, comparing non-pregnant women with a history of preeclampsia to women with a history of uncomplicated pregnancy." (PMID 27299886, 2016). "Similarly, the expression of SDC1, NPPB (natriuretic peptide B), GDF15 (growth differentiation factor 15), and ADAMTS6 (ADAM metallopeptidase with thrombospondin type 1 motif 6) all had a lower expression in our experimental exposures, and all are lower in preeclampsia." (PMID 34150771, 2021).
chronic kidney disease (10 papers, 2017 to 2024). Impairment of the renal function secondary to chronic kidney damage persisting for three or more months. "In congruence with our study, Padberg and colleagues demonstrated that plasma syndecan-1 levels increased across chronic kidney disease stages and were independently associated with renal dysfunction." (PMID 32531891, 2020). "Upregulation of Sdc-1 mRNA indicates the onset of an acute injury superimposed on chronic kidney disease." (PMID 34638892, 2021). "Sdc-1 shedding from eGC has been found to be elevated in individuals with chronic renal disease." (PMID 38074330, 2023). "Sdc-1 mRNA upregulation predicts the development of acute damage in chronic renal disease." (PMID 38074330, 2023). "Syndecan-1 serves as a biomarker of glycocalyx degradation and is released into the blood under stressful conditions such as AKI, chronic kidney disease, and cardiovascular disease." (PMID 38915464, 2024). "The degradation of the GCX has been observed in renal diseases such as chronic kidney disease (CKD), where vascular injury from fibrosis resulted in the upregulation of proteoglycans syndecan-1 and glypican-1." (PMID 39125975, 2024). "In one study of patients with chronic kidney disease, plasma syndecan-1 clearance was not a function of creatinine clearance." (PMID 28986821, 2017).